VCAN (versican)
Diseases named in the same sentence as VCAN in open-access papers (continued):
Sharing a sentence is not in itself a finding about the gene and the disease.
tumor (continued). "This core network of IL-19, TGFβ-1, CXCR4, BMP1, VCAN, and WNT2 reveals a tight-knit module that regulates tumor aggressiveness, immune evasion, and therapy resistance." (PMID 41348904, 2025). "We have screened and identified the key tissue/organ specific gene VCAN and found that the expression of VCAN is positively correlated with the occurrence of BCC and promotes the proliferation and migration of tumour cells." (PMID 40386063, 2025). "In comparison to non-tumor samples, it was observed that the protein levels of TGFβ-1, IL19, CXCR4, BMP1, VCAN, and WNT2 were significantly enhanced in several tumor samples." (PMID 41348904, 2025). "Increased expression of VCAN has been found in the TME in multiple cancers, such as breast, colon, lung, and liver, gastric cancers, contributing to tumor cell proliferation, metastasis, and resistance to apoptosis." (PMID 40542654, 2025). "Simultaneously, we validated VCAN expression in tumour samples from BCC patients and found that VCAN expression was higher than in normal skin samples, which was fully consistent with our bioinformatic findings." (PMID 40386063, 2025). "Tumor promoting CAFs displayed high expression of CCDC80, SFRP2, VCAN, COL8A1, RGS5, HIIGD1B, NOTCH3, and NDUFA4L2." (PMID 38525245, 2024). "We developed a novel immunohistochemical panel to assess prognostic outcomes and treatment sensitivity by detecting the expression of VCAN, CD3G, C1QB, CD68, CD4, and CD8 in both the TME and tumor cells of 190 DLBCL patients." (PMID 38980810, 2024). "CAF-derived periostin (POSTN) and versican (VCAN) play significant roles in CAF activation and tumor progression." (PMID 39200270, 2024). "Tumor-derived versican dampens DC function by binding to TLR2 and forming a positive feedback loop characterized by the upregulation of IL-10/IL-6 receptors, resulting in tumor immunosuppression." (PMID 38946426, 2024). "Taken together, our findings underscore the significant roles of VCAN, CD3G, and C1QB, which influence both the TME and the behavior of tumor cells." (PMID 38980810, 2024). "Versican is also responsible for altering the ECM by acting like a magnet for inflammatory cells and recruiting them to the tumor microenvironment." (PMID 38730679, 2024). "Their studies have demonstrated that the upregulation of CTHRC1, VCAN, and POSTN plays a pivotal role in the initiation of angiogenesis, hence facilitating the provision of essential nutrients to tumor cells." (PMID 38420016, 2024). "Little is known about the effects of VCAN cleavage, the functions of its fragments, or how this remodeling of the ECM affects the microenvironment and the phenotype of inflammatory or tumor cells present within it." (PMID 39682243, 2024). "We identified DEGs such as VCAN, SFRP2 involved in angiogenesis and epithelial-mesenchymal transition, which can be developed as novel tumor-agnostic biomarkers for tumor progression." (PMID 37965470, 2023). "VCAN, THBS1, and CCL20 were highly expressed in the Mono_2 cluster, which was derived from tumor tissue, indicating the potential of this specific monocyte cluster to exert a critical immunosuppressive effect." (PMID 37533434, 2023). "The drug effectively inhibited VCAN-induced NF-κΒ activation and cellular survival in RAW264.7 macrophages at the low micromolar range and blocked tumor growth in vivo at clinically relevant concentrations." (PMID 36980752, 2023). "VCAN IHC scores and TIM-3+ tumor-infiltrating immune cells (TIICs) were evaluated using 45 CRC specimens." (PMID 37894310, 2023). "Versican expression has been correlated with poor prognosis, increased TAM infiltration, poor tumor differentiation, and a higher tumor-grade metastasis (TNM stage) in a variety of cancers." (PMID 37784035, 2023).
tumor (continued). "Rather, C1QC+ TAMs showed enrichment of tumor vasculature, tumor angiogenesis, and ECM regulator pathways, while complement activation and cytokine pathways were significantly enriched in VCAN+ TAMs." (PMID 37383234, 2023). "A model consisting of four predictors (FIGO stage, residual tumor after surgery, and plasma levels of GSN and VCAN) showed the best predictive performance (mean validated AUC, 0.779)." (PMID 36669591, 2023). "We found that VCAN and MS4A4A expression was higher in tumor tissue compared with adjacent tissue of Neutrophils." (PMID 36569220, 2022). "The results were in accordance with the difference analysis of hub genes (ANGPT2, VCAN, MS4A4A, and FOS) between tumor tissues and normal tissue." (PMID 36569220, 2022). "Versican (VCAN) refers to a vital protein in the ECM, capable of accumulating in the tumor stroma; it can significantly regulate the malignant transformation of tumors and the progression of tumors as well." (PMID 36523602, 2022). "We also stained tumor sections for the core MI components COMP, FN1, CTSB, and VCAN, which were transcriptionally upregulated in PKN2KO tumors; stains were enhanced in invasive regions and in regions of connective tissue." (PMID 35081338, 2022). "To identify which cells are likely responsible for VCAN production and secretion, we performed scATAC-seq on NML, primary FLC tumor, and metastatic FLC tumor samples (n = 3)." (PMID 36923282, 2022). "Proteins of interest identified by tandem MS-MS that were decreased in sera from tumor-bearing rats that were either OKN-007-treated or untreated included ABCA2, ATP5B, CNTN2, ITGA3, KMT2D, MYCBP2, NOTCH3, and VCAN." (PMID 35053843, 2022). "From this study, proteins of interest identified by tandem MS-MS that were decreased in sera from tumor-bearing rats treated with OKN-007, compared to untreated, included ABCA2, ATP5B, CNTN2, ITGA3, KMT2D, MYCBP2, NOTCH3, and VCAN." (PMID 35053843, 2022). "The result showed that there were the co-existences of VCAN and FAP in the tumor, which was consistent with the analysis result at mRNA level." (PMID 36203562, 2022). "It is shown that CLEC7A, VCAN, and KYNU were significantly upregulated in monocytes, BIRC3 and SOD1 were mainly distributed in T cells, CCL20 was highly expressed in tumor cells, and CD69 was highly expressed in B cells." (PMID 35480896, 2022). "Based on subgroup analysis using clinicopathological features (tumor grade and cancer stage), we found that VCAN, EFNA4, and LUM have significantly higher expressions in patients with tumor grade than in healthy individuals." (PMID 34093807, 2021). "With this in mind, there may be therapeutic potential in targeting versican whose roles in immune exclusion we have shown here include providing vectors for immune cell trafficking through biochemical cues or contributing towards a stiff tumour matrisome through biophysical cues." (PMID 34527586, 2021). "The MIR4435-2HG- and ELFN1-AS1-associated ceRNA subnetworks affected and regulated the expression of the COL5A2, LOX, OSBPL3, PLAU, VCAN, SRM, and E2F1 target genes and were found to be related to prognosis and tumor-infiltrating immune cell types." (PMID 33750326, 2021). "In accordance with tumor staining results, we observed increased levels of IRF9 and VCAN in IRF9-overexpressing tumors; PCNA staining also showed an increase in PCNA expression in these tumors." (PMID 33430083, 2021). "Multiple genes, such as FBP1, PLOD2, VCAN, and CD44 have been demonstrated to participate in epithelial-mesenchymal transition (EMT) promotion of tumor metastasis." (PMID 33836688, 2021). "In a recent study, the proteoglycan versican (VCAN) and the glycoprotein tenascin C (TNC) also proved to be able to distinguish tumor from non-tumor tissues with high sensitivity and specificity, pointing to their use as cancer EVs markers." (PMID 33430152, 2021). "Hence, VCAN might exert function in the invasion and metastasis of tumor cells." (PMID 33604385, 2021).
tumor (continued). "EDA-containing FN, together with tenascin C, versican and periostin have also been found in other secondary sites prior to tumor cell arrival, and may be important for recruitment of stromal cells as well as for circulating tumor cells to the pre-metastatic niche." (PMID 32426283, 2020). "The interaction occurring among VCAN and TLR2 represents an effective link between inflammation and tumor progression." (PMID 33155039, 2020). "The tissue distribution and cell location of VCAN, CLIP4 and MATN3 proteins suggest their relevance to the tumor microenvironment (TME) 27-29." (PMID 32754268, 2020). "Thus, taken together, these studies establish that both intact versican and a proteolytic degradation product of versican have immunomodulatory properties and suggest that the anti-tumor properties of versikine might antagonize the pro-tumor properties of intact versican." (PMID 32265939, 2020). "The tissue distribution and cell localization of the VCAN, CLIP4 and MATN3 proteins suggest their relevance to the tumor microenvironment (TME)." (PMID 32754268, 2020). "Versican can also increase tumorigenesis by inducing cancer-cell self-renewal through EGRF signaling and by inducing cell survival, tumor growth and metastasis." (PMID 32984031, 2020). "Stromal VCAN expression is induced by TGFβ and IL6 and has been shown to regulate processes like tumour growth and invasion." (PMID 31336942, 2019). "In fact, it has been seen that the interaction between versican and CD44 affects the proliferation and motility of tumor cells." (PMID 31534630, 2019). "For VCAN, recent reports suggested that its cleavage by ADAMTS proteases can induce a general immunogenic response in the tumour microenvironment." (PMID 30166561, 2018). "Using OVCAR8 xenograft specimens we confirmed the inhibitory effect of LY on TGF-β signaling and tumor stromal expression of collagen type XI chain 1 (COL11A1) and versican (VCAN)." (PMID 30087253, 2018). "Recently, an integrated analysis of high-density copy number and gene expression data for 54 ccRCC tumours identified STC2 (5q35.1) and VCAN (5q14.3) as potential 5q oncogenes in ccRCCs." (PMID 28486536, 2017). "Immunostaining for versican GAGβ showed specific staining at the periphery of B16F10-, LLC- and MDA-MB231-tumors, with the LLC tumors showing also strong staining in the tumor center." (PMID 29222454, 2017). "This leads to the conclusion that lumican expression may be increased in a more progressed disease state independent of specific tumor progression-associated chromosomal aberrations, while increased stromal versican expression may be induced by factors directly regulated by gain of chromosome 13q." (PMID 28481899, 2017). "Compared to hATN, we found increased expression of versican, Adipo R1 and CD44 both in hATT attached to the tumor as well as in hATT 2 cm from the tumor." (PMID 28173833, 2017). "We next sought to determine the origin of versican in the MDA-MB231 tumors, which contain both human tumor cells and stromal cells of mouse origin." (PMID 29222454, 2017). "To determine the influence of host versican on tumor angiogenesis, we compared tumor growth and tumor angiogenesis in B16F10 tumors formed in Vcanhdf/+ mice (haploinsufficient for versican), and wild-type littermates." (PMID 29222454, 2017). "Neural lineage markers, such as NCAM1 (early) and NPTX1 (neuronal), were highly expressed in 143BNSC tumours, whereas genes involved in cancer proliferation, including EYA2, VCAN, HMGA1 and TXNIP, were highly expressed in 143BGBM tumours." (PMID 27551510, 2016). "Versican, an extracellular matrix (ECM) proteoglycan produced by tumor cells, stromal cells and leukocytes, is markedly increased in inflammation and known to stimulate inflammatory cytokine released by immune and inflammatory cells." (PMID 26777116, 2016).
tumor (continued). "Tumor lesions following intraperitoneal injection of spheroids that were deficient for versican expression demonstrated a delay in seeding such that no lesions were present at five and a half weeks for both clones while tumors could be identified although at a much lower level after ten weeks." (PMID 24999371, 2014). "Kim and colleagues demonstrated that Lewis lung carcinoma cells produced a large amount of versican that activated macrophages via TLR-2/TLR-6 and enhanced metastatic tumor growth." (PMID 25125485, 2014). "Overexpression of NETO2, VCAN, and GBP2 in tumor tissues compared to normal tissues were observed in 93.75% (15/16), 93.75 (15/16), and 87.5% (14/16), respectively." (PMID 24783204, 2014). "Recent studies of the tumor microenvironment have demonstrated Lewis lung carcinoma (LLC) cells produced factors, such as versican, are necessary for lung tumor growth and metastasis." (PMID 23424670, 2013). "We performed RNAi knockdown experiments to further assess versican V1 influence on macrophage TLR2/6 activation, hCAP18/LL-37 induction, and subsequent tumor cell proliferation and invasion." (PMID 23424670, 2013). "COL1A1, hyaluronan (HA), versican (VCAN), periostin (POSTN) and matrix metalloproteinase (MMP) 9 are all increased and the magnitude of these responses are related to tumor aggressiveness." (PMID 24213323, 2012). "Interestingly, ligation of TLR2 by versican appears to be directly involved in the activation of multiple types of cells in tumour stroma, including macrophages, and the induction of inflammatory cytokine secretion to generate an inflammatory microenvironment hospitable for tumor progression." (PMID 20871832, 2010). "Interaction of versican with the extracellular matrix (ECM) and cell surface proteins is believed to enhance structural integrity between tumor and stromal tissues and regulates cell proliferation and metastatic potential." (PMID 21079779, 2010). "The present study suggests a potential significant role of the G3 domain of versican with its EGF-like motif in influencing tumor cell viability, proliferation, and local tumor growth." (PMID 17662123, 2007). "A comparison of these with the 683 KPTN tumor–upregulated genes revealed 130 consistently upregulated genes, including ECM components (COL4A1, COL4A2, COL12A1, VCAN, etc.)and YAP targets (ANKRD1, AXL, CYR61, F3)." (PMID 41480763, 2026). "The N‐terminal G1 domain of VCAN, which includes an immunoglobulin (Ig) homolog module and two hyaluronan‐binding domains, binds to hyaluronan and interacts with CD44, stimulating tumor spreading, self‐renewal, and angiogenesis, while reducing matrix permeability." (PMID 40542654, 2025). "Due to lack of space, we will refer to decorin (SLRP) and versican (hyalectan), two extracellular proteoglycans with often contradicting functions in tumor biology." (PMID 40542654, 2025). "Proteins such as periostin (POSTN), versican (VCAN), collagen type XI alpha 1 (COL11A1), and collagen triple helix repeat containing-1 (CTHRC1), through TGF-β signaling, participate in CAF activation and promote tumor progression." (PMID 40136652, 2025). "In the present study, we aimed to investigate the impact of CAFs on tumor cell-intrinsic cGAS–STING expression in CRC, by analyzing the correlation between tumor cell-intrinsic cGAS–STING expression and the stromal expression of versican (VCAN), an immunosuppressive CAF-specific marker in CRC29,30." (PMID 40451897, 2025). "VCAN, CD3G, and C1QB were three key genes that influenced the tumor purity of DLBCL, and could also exert certain impact on drug sensitivity and prognosis of DLBCL patients." (PMID 38980810, 2024). "Notably, BCAN, VCAN, and JAM2 were predominantly expressed by tumor cells, while ITGB1 was ubiquitously expressed across all clusters." (PMID 39554845, 2024).
tumor (continued). "Both VCAN and XRCC4 have been reported to be regulated by MAPK/AP1 signaling in tumor cells, but the specific regulatory elements driving tumor-specific expression of these genes are unknown." (PMID 39018396, 2024). "Some studies show that the bioactive fragments of VCAN (matrikines) generated by the action of the ADAMTS enzymes can contribute to regulating the inflammatory infiltrate and antitumor immune response in various neoplasms." (PMID 39682243, 2024). "Indeed, versican predominantly binds to HA in tumours and degradation of the HA matrix with PEGPH20 will act in part by altering versican and versikine distribution, with repercussions on myeloid and lymphocyte recruitment." (PMID 38791926, 2024). "The concordant changes in protein expression results with the values detected at the gene expression can be observed in all the evaluated parameters of integrin αV, brevican, CSPG-5, versican, integrin β-5, and CD44 and only in tumor staining in the case of MDM2, MMP2, and FLT-4." (PMID 39595920, 2024). "Unlike versican, which consistently promotes tumor progression, decorin appears to have a more multifaceted role in cSCC." (PMID 38730679, 2024). "As a result, the value of versican as a novel tumor marker for NSCLC has not yet been thoroughly assessed." (PMID 37259101, 2023). "These clinical data have significance in that VCAN expression increases as the severity of BLCA progresses, suggesting VCAN can not only distinguish LVI(+) and LVI(−) genes but also indicate the degree of tumor malignancy in patients." (PMID 37108649, 2023). "The pro-inflammatory interplay between VCAN in tumor cells and IKKβ in macrophages described here is not only mechanistically intriguing, but also promising for innovations in cancer therapy and diagnosis." (PMID 36980752, 2023). "Versican has been shown to have a role in the promotion of angiogenesis in malignant tumors by interacting with fibronectin, vascular endothelial growth factor(VEGF), HA, and other molecules in the tumor microenvironment." (PMID 37259101, 2023). "We found that the levels of tumor-infiltrating TIM-3+ immune cells, mainly M2-like macrophages, were correlated with tumors exhibiting TGFβ-activated stroma, as detected by VCAN staining, and that TIM-3+ cells particularly accumulated in VCANHigh stromal areas." (PMID 37894310, 2023). "Notably, VCAN+ TAMs were reprogrammed into C1QC+ TAMs with upregulated coinhibitor and downregulated coactivator expression in the tumor region, suggesting key roles of C1QC+ TAMs in the tumorigenesis of HCC." (PMID 37383234, 2023). "In this study, we found that the hub genes including VCAN MS4A4A, and FOS could regulate the differentiation of monocytes in the tumor environment." (PMID 36569220, 2022). "Specifically, VCAN protein is variable but abundant in the tumor tissue from all 3 patients with FLC, while virtually absent in the adjacent nonmalignant samples (bottom)." (PMID 36923282, 2022). "Four of 13 overlapped markers (MXRA8, CLMP, VCAN and FBLN1) are involved in cell adhesion and tumor metastasis, suggesting that dysfunctions in cell adhesion pathways could lead to anti-PD-1 resistance associated by RIPK1 and AXL." (PMID 36518525, 2022). "Firstly, tumor cells secrete Tsp2 to induce the transformation of normal fibroblasts to TAFs, and TAFs remodel the extracellular matrix by secreting COL1A1, COL1A2, COL5A1, FN1, and VCAN." (PMID 35982904, 2022). "Through the analysis of multiple omics and independent cohorts, we comprehensively explored the negative effect of VCAN on anti-tumor therapeutic efficacy and its potential mechanisms." (PMID 36203562, 2022). "A proteomic analysis of colorectal normal and tumor ECM revealed that collagen IV, V and XIV, fibrilin, emilin, vitronectin, laminin and endomucin have increased expression in tumor ECM, and that periostin, versican, thrombospondin-2 and tenascin were exclusively present in tumor tissue." (PMID 35053521, 2022).